MIR382 (microRNA 382)
Synonyms: hsa-mir-382; MIRN382; mir-382
Gene: MicroRNA gene on chromosome 14 (101,054,306 to 101,054,381, forward strand). Ensembl gene ENSG00000283170.
Gene Ontology:
Biological process: miRNA-mediated post-transcriptional gene silencing
Cellular component: RISC complex
Homologues: Orthologues: chimpanzee ptr-mir-382 (100% identical), guinea pig MIR382 (100% identical), mouse Mir382 (99% identical). Paralogues in human: MIR487A (79% identical), MIR539 (79% identical), MIR494 (76% identical), MIR154 (75% identical), MIR323A (66% identical), MIR377 (66% identical), MIR410 (66% identical), MIR381 (64% identical), MIR487B (64% identical), MIR323B (63% identical), MIR496 (62% identical), MIR1185-1 (59% identical), and 4 more.